LGR5 (leucine rich repeat containing G protein-coupled receptor 5)
Diseases named in the same sentence as LGR5 in open-access papers (continued):
Sharing a sentence is not in itself a finding about the gene and the disease.
tumor (continued). "The HH and Wnt pathways can jointly induce CSC biomarkers, such as CD44, CD133, BMI1, and LGR5, and promote EMT, thereby promoting tumor cell infiltration and distant metastasis and allowing tumor cells to obtain stem cell characteristics and drug resistance capacity." (PMID 35719973, 2022). "The LGR5 marker, which is one of the key markers of intestinal stem cells, was very highly expressed in both WIDR and SW480 cell lines derived from a primary patient tumor." (PMID 35892561, 2022). "Quantification showed that only one tumor sample exhibited a significant number of HRCs co-expressing the LGR5 signature (7.79% sample SMC04) whereas five others included a minimal fraction (<3%) of cells marked by both LGR5 and the HRC gene programs." (PMID 36352230, 2022). "Here we show that humanized ISC signature scores (Hu-EphB2-ISC; Hu-Lgr5-ISC), but not non-stemness signature scores such as Hu-Late TA and Hu-Proliferation, were significantly associated with tumor progression in 2191 Stage I-IV (primary) and metastatic CRCs." (PMID 35272617, 2022). "A clinical study has reported that 77 out of 188 HCC specimens showed positive staining for Lgr5, and the occurrence frequency of Lgr5 in tumor area was remarkably higher than that in the non-tumor area." (PMID 36168631, 2022). "Again, effective ablation of Lgr5+ cells in the iCT model neither altered CRC tumor growth nor prevented metastatic recurrence." (PMID 36352230, 2022). "The expression patterns of several WNT/intestinal stem cell marker genes confirmed that HRCs were not LGR5+ stem-like tumor cells." (PMID 36352230, 2022). "The authors elucidated that differentiated tumor cells characterized by expression of KRT20, could revert to LGR5+ cells, to fuel tumor growth." (PMID 34095127, 2021). "We also found that HDGF and LGR5 co-localized morphologically in the microvasculature regions, suggesting that HDGF and LGR5 might both be involved in tumor angiogenesis and cancer stemness." (PMID 34106558, 2021). "Expression of CK19, SOX9, LGR5, and LRIG1 in MCC and normal human skin was studied by immunohistochemistry, and the staining patterns or intensities were statistically correlated with patient, tumor, MCPyV, and survival parameters." (PMID 34331569, 2021). "Since inflammation is a key determinant of a pro-tumorigenic environment, it is perhaps unsurprising that the inflammatory mediator PGE2 drives expansion of multiple CSC populations (expressing LGR5, CD133, CD44, and SOX2) and promotes liver metastasis in orthotopic tumour models." (PMID 33673710, 2021). "Notably, LGR5− cells can produce LGR5+ cells and contribute to tumor regrowth after LGR5+ cell ablation, indicating cellular plasticity." (PMID 33711267, 2021). "In a spontaneous metastasis model derived from orthotopic tumors, the ablation of Lgr5+ cells did not provoke regression of the primary tumor but abrogated the formation of metastases in the liver." (PMID 33671641, 2021). "Material from the regrown tumor was collected to establish an isogenic model of carboplatin-resistant TNBC (C4O) and gene expression analysis revealed changes in Wnt signaling target AXIN2 and pluripotency and stem markers NANOG, OCT4, SOX2, and LGR5." (PMID 34367990, 2021). "Unexpectedly, ablation of Lgr5DTR CSCs did not impair primary tumour invasiveness per se, yet still reduced liver metastatic burden, raising the possibility of LGR5-independent mechanisms of productive invasion." (PMID 33673710, 2021). "The up-regulated genes such as DSG3 and LGR5 might facilitate tumor metastasis, while the downregulation of ITGA3 changed the extracellular matrix and might promote tumor expansion." (PMID 34222020, 2021). "Likewise, lineage tracing in CRC cancer models has revealed preferential outgrowth of cancer cell subpopulations defined by expression of genes such as LGR5 or IL17RB or by localization at the leading edge of the tumor." (PMID 34409732, 2021).
tumor (continued). "Our findings in this study corroborated the tumor-suppressive roles of miR-142-3p, in that transfection of CRC cells with miR-142-3p mimic molecules resulted in decreased expressions of LGR5, β-catenin, mTOR, and IL-6 as well as reduced SPs, as a surrogate of reduced ABCG2 expression." (PMID 32560222, 2020). "Immunohistochemistry showed that Lgr5 protein was absent in all HF tumour samples analysed, despite the presence of positive immunostaining in the hair follicles of the skin surrounding the tumour mass." (PMID 32397255, 2020). "Hence, identical numbers of FACS-sorted LGR5–GFP+ and LGR5–GFP− cells derived from primary liver tumors were subcutaneously engrafted into NOG mice, and tumor formation was monitored." (PMID 32327656, 2020). "All tumor cells express Confetti-RFP (red), and Lgr5+ CSCs additionally express eGFP (green)." (PMID 32169167, 2020). "Hence, we challenged tumor organoids with sorafenib, the FDA-approved drug for treating advanced HCC, and compared the relative potential of LGR5–GFP+ and LGR5–GFP− cells to withstand such treatment." (PMID 32327656, 2020). "Taken together, these findings have demonstrated that LGR5+ AM-EpiSCs can surmount resistance to the BRAFV600E inhibitor (PLX4032) and these PLX4032-resistant LGR5+ AM-EpiSCs are endowed with stem cell properties and an intermediate EMT phenotype with enhanced capacity for tumor organoid formation." (PMID 32382005, 2020). "Essentially, CRC tumor-spheres treated with MSI-N1014 showed significantly reduced expressions of LGR5, β-catenin, and ABCG2, and reduced resistance against 5-FU, with an increased level of microRNA (miR)-142-3p, which targets both LGR5 and ABCG2." (PMID 32560222, 2020). "The overall LGR5/Oct4 expression in phenotypically plastic l.t.EMT+RGM1 cells suggests their stem-cell like pluripotency commitment, which is potentially relevant for tumor development." (PMID 33023180, 2020). "In this study, we identified a putative subpopulation of LGR5+ epithelial cells with stem-like cell properties characteristic of a hybrid EMT phenotype, elevated self-renewal and tumor-propagating capabilities, and resistance to a selective BRAFV600E inhibitor." (PMID 32382005, 2020). "Impressively, the diphtheria toxin-induced ablation of Lgr5+ CSCs in liver metastases resulted in tumor regression, and the growth of metastatic tumors was not renewed after the administration of diphtheria toxin was stopped." (PMID 30934773, 2019). "The results of IHC shown that almost all the tumor cells were Lgr5 absolutely positive or absolutely negative." (PMID 31417548, 2019). "Also, Lgr5 is known to exhibit tumor-suppressive activity in the colon, which results from suppression of tumor growth and metastasis regulated by RSPO1/Lgr5-mediated activation of TGFβ signaling." (PMID 31358061, 2019). "Finally, tumor size, degree of differentiation, TNM stage, Lgr5 expression level, and intratumor FoxP3+ Tregs were included in a multivariate Cox proportional hazards analysis." (PMID 31417548, 2019). "Furthermore, in the fresh tumor tissues, the level of TGF-β1 in the high Lgr5 expression group were much higher compared with the low Lgr5 expression group (P < 0.0001; 194.77 ± 93.74 pg/ml vs. 105.13 ± 71.90 pg/ml)." (PMID 31417548, 2019). "The tumours that arose were deficient for BCL9, and despite being positive for nuclear β-catenin, were also negative for Lgr5." (PMID 30760720, 2019). "The interaction between Lgr5 and the immune-related tumor microenvironment is not completely understood." (PMID 31417548, 2019). "In xenograft studies it was shown that specifically targeting the Lgr5+ cells through antibody-drug conjugated therapy, or directly genetically, indeed inhibits tumor growth without affecting intestinal epithelium homeostasis." (PMID 30927915, 2019). "Interestingly and importantly, in LGR5+ or DCLK1+ cells of established colorectal tumors, HES1 deletion induced immediate apoptosis, thus consistently reducing the tumor burden." (PMID 29652830, 2018).
tumor (continued). "Thirty-six cases with negative expression of Lgr5 were confirmed with negative immunostaining in one additional tumor block of every CRC case." (PMID 30046385, 2018). "Furthermore, in normal LGR5+ cells, HES1 deletion and β-catenin stabilization decreased tumor formation and prolonged host survival." (PMID 29652830, 2018). "In summary, the present study demonstrates that LGR5 is overexpressed in EOC tumor samples and that dysregulated LGR5 expression, which occurs frequently in EOC, promotes tumor proliferation, metastasis, and EMT of EOC cells through the Notch1 signaling pathway." (PMID 29777575, 2018). "Should LGR5 also regulate MEK/ERK signalling in CRC cells, this could alter tumour behaviour substantially, particularly during the stages of CRC development where a KRAS mutation (which constitutively activates MAPK signalling) has not yet been accrued." (PMID 29844449, 2018). "Also in this case, an initial compensatory proliferation of remaining LGR5−/KRT20+ cells is observed, but it is insufficient to ensure tumor volume maintenance." (PMID 29853913, 2018). "A Kaplan-Meier analysis showed that, in the non-TNBC group, patients with high levels of tumor LGR5 expression exhibited significantly shorter RFS periods compared to patients with low levels of LGR5 expression (p = 0.033)." (PMID 29471794, 2018). "Lgr5 expression was not significantly related to patient age, gender, tumor size, tumor location, tumor differentiation and lymphovascular invasion (P > 0.05)." (PMID 30046385, 2018). "Cell scratch‐wound and tumor cell invasion assays in vitro indicated that overexpression of LGR5 remarkably promoted the migration and invasion capacity of EOC cells, while the opposite results were observed on LGR5 knockdown." (PMID 29777575, 2018). "Lgr5, VEGF expression levels and microvessel density (MVD) were detected in tumor tissue." (PMID 28404940, 2017). "Depletion of Lgr5+ TIC significantly decreased established tumor burden at metastatic sites or their formation in different metastasis models, demonstrating that Lgr5+ tumor cells play an important role for metastasis initiation and maintenance." (PMID 28559443, 2017). "Only one characteristic of tumor cells, such as expression of Bmi1 or Lgr5, seem not be sufficient to define the competency of being introduced with multiple mutations." (PMID 28176811, 2017). "Our data clearly show that in the C3-1-Tag model, Lgr5 function is clearly unnecessary for tumor initiation or progression, and that in such a model an anti-Lgr5 therapy would not be efficacious." (PMID 28649656, 2017). "In 139 pairs of tissues, 88.5% (123/139) of HCC tumor tissues showed positive expression of LGR5, so did 11.5% (13/139) of the adjacent non-tumor tissues." (PMID 28881613, 2017). "In addition, most patients with a cluster of genes for ABCB5, Lgr5, and CD133 were derived from group I that developed metastases and/or died tumor related." (PMID 34221246, 2017). "The knockdown of LGR5 resulted in significantly reduced growth of A431 cells in culture and tumor weight after seeding 3 × 106 of A431 cells (with or without LGR5 knockdown) into nude mice." (PMID 27049829, 2016). "Thus, 20 tumor cells isolated from either control, CXCR4+/Lgr5-, Lgr5+/CXCR4- or Lgr5+/CXCR4+ cells were transplanted s.c. into new NOD/SCID mice." (PMID 27835894, 2016). "The Lgr5+ stem cells did not appear to become tumor-initiating cells in skin carcinogenesis by exogenous agents." (PMID 27409834, 2016). "In contrast to CD34/K15+ quiescent bulge stem cells, actively proliferating Lgr5+ stem cells do therefore not appear to be tumor drivers in experimental skin carcinogenesis." (PMID 27409834, 2016). "Lgr5+ stem cells were absent in the ultimate tumor masses, and no tumor appeared to be a (clonal) expansion of Lgr5+ cells (52 tumors with tamoxifen at the start of carcinogenesis, 42 tumors with tamoxifen late during tumor outgrowth)." (PMID 27409834, 2016).
tumor (continued). "Most Lgr5+ stem cells that we observed were located in hair follicle-like structures below or neighboring the tumor mass and none in the tumor mass itself (data not shown)." (PMID 27409834, 2016). "KLF4 deletion by Lgr5-Cre and Rosa-Cre induced precancerous changes but did not induce tumor formation within 2 weeks of KLF4 deletion." (PMID 27277677, 2016). "R-spondins (RSPO) and their receptor LGR5 are required for optimal canonical WNT signaling, but expression was insignificant in all samples (LGR5) or was found in tumor cells from a subset of patients only (RSPO genes)." (PMID 27215396, 2016). "The reverse correlations suggested that lgr5 methylation was related to cancer of a less invasive phenotype, i. e., higher tumor grade, negative lymph node and distant metastasis, which was further supported by the Kaplan-Meier survival analysis." (PMID 26599100, 2015). "In the present study, licofelone significantly suppressed increases in DclK1 along with other CSC markers (Lgr5, CD133 and CD44) in correlation with its inhibition of tumor progression, suggesting that licofelone may kill CSCs." (PMID 25906749, 2015). "It will therefore be of great interest to examine LGR5 expression in a larger cohort of patients using immunohistochemistry to evaluate its prognostic significance, and assess its correlation with phosphorylated MEK/ERK/Akt in primary tumours." (PMID 26517508, 2015). "Furthermore, we found while individual knockdown of either REG4 or LGR5 partially inhibited tumor cell growth in nude mice, the double REG4/LGR5 knockdown inhibited tumor growth to an extent similar to the GATA6 knockdown." (PMID 26387746, 2015). "Lgr5 knockdown was shown to induce cell death, and furthermore, a recently-developed monoclonal antibody (KM4056) was reported to have potent complement-dependent cytotoxicity activity in vitro, and to show strong anti-tumor activity in vivo." (PMID 24666414, 2014). "It has been hypothesized that stem cells are more abundant in tumours than in normal mucosa and we also observed that there was a clear overexpression of LGR-5 compared to the normal mucosa in MDF and tumours." (PMID 23374535, 2013). "Based on its prevalent localization at the base of normal crypts, as expected for stem cells, and on the overexpression in precancerous lesions and tumours, we support LGR-5, but not MSI-1 or DCAMKL-1, as putative neoplastic stem cell marker." (PMID 23374535, 2013). "First, because technical limitations precluded the specific microdissection of Lgr5+ cells, we compared the levels of ISC markers in the upper and lower regions of tumor glands and not in LGR5-positive and -negative tumor cells." (PMID 24340024, 2013). "Recent study suggests that LGR5 is expressed in the remaining islets and in ductal cancer cells in cancerous pancreas, therefore, pancreatic islets beta cells contain cells-of-origin of PDA that express their unique markers in the PDA tumor cells." (PMID 24133453, 2013). "Additionally, POU5F1, LGR5 and CCND1 were analysed, and tumour samples of patients with TRG2 or TRG3 (each n = 22) were studied." (PMID 22970250, 2012). "Interestingly we also observed an increased expression of LGR5, a promising intestinal CSC marker, after chemotherapy in tumours with TRG2." (PMID 22970250, 2012). "LGR5 seems to be a more general marker of stemness in the gastrointestinal tract, helping to raise novel hypothesis for the involvement of CSC in tumour development, progression and growth patterns." (PMID 22530031, 2012). "The expression of LGR5 by tumour cells did not correlate with any clinico-pathological patient characteristic, including patient survival." (PMID 22530031, 2012). "LGR5 staining was decreased, but not totally absent, in tumours derived from LIM1899 cells transfected with siLGR5." (PMID 21829496, 2011). "No expression of the putative stem cell marker (LgR5) was detected in normal esophageal squamous cell epithelium, adjacent to the tumor." (PMID 21345220, 2011).
tumor (continued). "An additional advantage of a BsAb is that a second binding arm directed to a tumor-specific antigen may facilitate preferential targeting of the LGR5+ stem-cell-like cell within a tumor rather than an LGR5+ ISC." (PMID 40427162, 2025). "Remarkably, Lgr5 cells were not able to drive tumor formation." (PMID 40060632, 2025). "In the present study, ONC201 treatment did not suppress either c-Myc or LGR5 expression, which may have led to the failed decrease in tumor vessel formation within non-MYCN-amplified NB xenografts." (PMID 40210723, 2025). "Indeed, petosemtamab has been shown to be more effective than cetuximab in various preclinical models of cancer that express both LGR5 and EGFR, in terms of inhibiting organoid growth in vitro and inhibiting xenograft tumor growth or the outgrowth of metastases in vivo." (PMID 40427162, 2025). "However, targeting LGR5+ CSCs as a therapeutic strategy remains contentious, as LGR5 ablation does not significantly impair tumor growth." (PMID 40661135, 2025). "LGR5+ depletion suppressed CRC growth and LGR5+ cells could re-initiate tumor growth in vivo." (PMID 39821694, 2025). "Specific genes downregulated in HG tumours which showed significantly higher promoter methylation included the developmental transcription factors CDX1, CDX2, GATA6, HNF1A, the marker of colonic differentiation, DPP4, and the markers of LGR5+ intestinal stem cells, ASCL2, LGR5." (PMID 40473896, 2025). "The majority of functional studies have shown that LGR5 plays an important role in promoting cancer progression, metastasis and chemotherapy resistance however, in some contexts LGR5 can also activate tumor-suppressive pathways and LGR5 negative cells can also promote cancer progression." (PMID 39821694, 2025). "LGR5 is an established stem cell marker in a number of murine tissues, is overexpressed in a range of cancers, and studies using genetically engineered mouse models (GEMMs) and human CRC organoids have found that LGR5 is critical for maintaining the proliferative compartment in tumours." (PMID 39169164, 2024). "Therefore, LGR5 expression is elevated in tumours with clinical and molecular features of the non-proliferative HCC sub-class." (PMID 39169164, 2024). "Indeed, there are several biological features supporting the MACC1-LGR5 link, i.e., the involvement of MACC1 and of LGR5 in clathrin-mediated endocytosis, their localization at the tumor invasion front, their role in core clock regulation and their impact on craniofacial development." (PMID 38339354, 2024). "Interestingly, ablation of Lgr5(+) CSCs did not inhibit the growth of the primary tumor, as Lgr5(+) CSCs were continuously replenished by proliferative Lgr5(−) cancer cells, but resulted in reduced liver metastasis (CRLM)." (PMID 37760539, 2023). "However, selective and effective killing of Lgr5+ cells had no impact on primary tumor growth, and cells that disseminate and colonize distant organs were frequently Lgr5−." (PMID 38140103, 2023). "Interestingly, selective ablation of Lgr5(+) cells reduced the growth of the primary tumor, but did not result in tumor regression, and there was even rapid tumor recurrence by proliferating Lgr5(−) cells that replenished the pool of Lgr5(+) CSCs." (PMID 36835075, 2023). "Furthermore, Lgr5+ CSC depletion did not lead to tumor regression since Lgr5− cells were able to repopulate the Lgr5+ cell pool." (PMID 36358834, 2022). "However, higher levels of the markers LGR5 and BMI1 were observed in CPP35 (tumor-invaded peritoneum) compared to CPP14 (early-stage tumor), which may be explained as for the cell lines by the location of the original tumor." (PMID 35892561, 2022). "Furthermore, high levels of POLR1A define a stemness compartment independent of LGR5 expression and drive in vivo tumor formation of LGR5 low cells." (PMID 35673898, 2022).